HJURP (Holliday junction recognition protein)
Description:
Centromeric protein that plays a central role in the incorporation and maintenance of histone H3-like variant CENPA at centromeres. Acts as a specific chaperone for CENPA and is required for the incorporation of newly synthesized CENPA molecules into nucleosomes at replicated centromeres. Prevents CENPA-H4 tetramerization and prevents premature DNA binding by the CENPA-H4 tetramer. Directly binds Holliday junctions.
Synonyms: FAKTS; URLC9; DKFZp762E1312; hFLEG1
Tractability: PROTAC: UniProt records ubiquitination sites on it; ubiquitination databases record sites on it.
Gene: Protein-coding gene on chromosome 2 (233,833,416 to 233,854,566, reverse strand). Ensembl gene ENSG00000123485.
Subcellular location: Nucleus, nucleolus; Chromosome, centromere
Subcellular location (Human Protein Atlas): Nucleoli; Nucleoplasm; Cytosol
Pathways (Reactome):
Cell Cycle: Cyclin A/B1/B2 associated events during G2/M transition; Deposition of new CENPA-containing nucleosomes at the centromere
Gene Ontology:
Molecular function: histone binding; identical protein binding; protein binding
Biological process: CENP-A containing chromatin assembly; chromosome segregation; regulation of DNA binding; regulation of protein-containing complex assembly
Cellular component: chromosome, centromeric region; kinetochore; nucleolus; nucleoplasm; nucleus
Genetic constraint (gnomAD): Loss-of-function variants: 36 observed, 59.07 expected, observed/expected ratio (o/e) 0.61, 90% interval 0.47 to 0.81. The upper end of that interval is the gene's LOEUF score, 0.81, which puts it in group 3 of 6, group 1 being the genes least tolerant of losing a copy. Missense variants: 795 observed, 869.84 expected, observed/expected ratio (o/e) 0.91, 90% interval 0.86 to 0.97. Synonymous variants: 323 observed, 328.09 expected, observed/expected ratio (o/e) 0.98, 90% interval 0.9 to 1.08.
Homologues: Orthologues: chimpanzee HJURP (95% identical), macaque HJURP (85% identical), pig HJURP (54% identical), dog HJURP (52% identical), guinea pig Hjurp (47% identical), rat Hjurp (41% identical), mouse Hjurp (41% identical).
Diseases named in the same sentence as HJURP in open-access papers:
HJURP is named in the same sentence as 67 diseases in open-access papers, as found by Europe PMC text mining. Sharing a sentence is not in itself a finding about the gene and the disease. The quoted sentences say what the papers report.
breast carcinoma (35 papers, 2010 to 2025). "Our bioinformatics analysis and cell biology experiments revealed that HJURP is abnormally overexpressed in breast cancer and is associated with a poor prognosis." (PMID 39139392, 2024). "As a diagnostic or prognostic biomarker, HJURP expression is relevant with the prognosis of several cancer types including colon cancer, breast cancer, and hepatocellular carcinoma." (PMID 35965590, 2022). "Rationale for choosing APLF and HJURP amongst all other histone chaperones is that, APLF over-expression is associated with TNBC/basal type breast cancer metastasis while HJURP over-expression is associated with luminalA breast cancer metastasis." (PMID 32257110, 2020). "Higher expression of HJURP has been associated with breast cancer progression of different subtypes (ER−, PR−) and associated with shorter survival." (PMID 32257110, 2020). "Increased HJURP expression in luminal A subtype breast cancer progression associated with the increase in probability of metastasis." (PMID 32257110, 2020). "Although, it has been reported that elevated levels of HJURP are associated with higher sensitivity to radiation in breast cancer cells, it is known that protein function can vary significantly in different cell types." (PMID 23638004, 2013). "Overexpression of HJURP, the mammalian homolog of budding yeast Scm3p, has been observed in lung and breast cancers and is associated with poor prognosis; however, the physiological relevance of these observations is not well understood." (PMID 21980305, 2011). "We assessed the association between HJURP mRNA levels and clinical factors and outcomes using a cohort of breast cancer patients in our previous studies." (PMID 20211017, 2010). "The associations of the Panel 2 markers MAL2, EMP2, CCNE2 and HJURP with short OS may point to different biological characteristics of the enriched cells and warrant further studies in aggressive breast cancer subtypes." (PMID 36831613, 2023). "We investigated whether altered expression levels of HJURP are associated with adverse clinical outcomes using cohorts of patients with breast cancer." (PMID 20211017, 2010). "High HJURP mRNA expression is significantly associated with both shorter disease-free and overall survival which were validated in five independent clinical datasets for breast cancer." (PMID 20211017, 2010). "To test this hypothesis, we firstly performed Kaplan–Meier analyses using the online Kaplan–Meier–Plotter breast cancer database and the results showed that high expression of YAP1 mRNA level is associated with poor recurrence-free survival (RFS) in breast cancer patients with high HJURP expression." (PMID 35459269, 2022). "The evidences include: overexpression of MCM2 in gastric tumors predicted poor prognosis in the patients; knock down of HJURP reduced the sensitivity of breast cancer patients to radiation treatment; the loss of CHD8 may be an indicator for biological aggressiveness in gastric cancer." (PMID 25390899, 2014). "A recent study demonstrated that the expression of HJURP is higher in triple-negative breast cancer than in other breast cancer subtypes." (PMID 40004168, 2025). "The expression level of HJURP has been shown to have an independent prognostic impact and can predict sensitivity to radiotherapy in breast cancer." (PMID 40290723, 2025). "Holliday junction recognition protein (HJURP), an oncogene involved in tumor progression and associated with poor prognosis, is aberrantly expressed in various tumors, including breast cancer, multiple myeloma, pancreatic cancer, and PCa." (PMID 39405980, 2024). "Analysis of a large panel of breast cancer (BC) cell lines revealed upregulated levels of HJURP expression in approximately 50% of cell strains, compared to immortalized non-malignant breast epithelial cells." (PMID 37025176, 2023).
breast carcinoma (continued). "The expression of HJURP is relatively higher in TNBC cells compared with other types of breast cancer cells, which is consistent with previous work." (PMID 35459269, 2022). "Previous work showed that HJURP is lower expressed in luminal A breast cancer than in other types of breast cancer and can distinguish between good and poor prognosis in luminal A breast cancer patients." (PMID 35459269, 2022). "Interestingly, we found that HJURP was positively associated with dysfunctional T cells, but hypomethylation of HJURP was correlated with the shorter OS in different tumors including glioma, melanoma, renal clear cell carcinoma, renal papillary carcinoma, breast cancer and cholangiocarcinoma." (PMID 36460821, 2022). "Recent studies have shown that HJURP plays a dual role in the progression of glioblastoma, prostate cancer, and breast cancer." (PMID 35459269, 2022). "Additionally, high HJURP mRNA expression was also significantly associated with both shorter disease-free and overall survival and could predict the sensitivity of radiotherapy in breast cancer." (PMID 35459269, 2022). "According to TCGA database and GEPIA, HJURP was upregulated in many types of cancers compared with the para-tumor tissues, including bladder urothelial carcinoma, breast cancer, and colon cancer." (PMID 35965590, 2022). "The significant association between the expression of HJURP and the prognosis of patients revealed that HJURP was a general biomarker for breast cancer." (PMID 35274047, 2022). "Highly expressed HJURP gene expression and its transcriptional signature are reported in many cancer types, such as hepatocellular carcinoma, glioma, breast cancer, and bladder cancer." (PMID 35274047, 2022). "In the field of breast cancer research, the expression of HJURP in breast cancer is significantly higher than that in normal tissues." (PMID 35459269, 2022). "In hepatocellular carcinoma, prostate cancer, ovarian cancer, and breast cancer, IHC showed that HJURP was mainly expressed in cell cytoplasm; nevertheless, HJURP was mainly observed in cytoplasm in pancreatic cancer and colorectal cancer." (PMID 35965590, 2022). "In fact, HJURP has been reported to be a better biomarker than Ki67 for assessing the proliferation rate in luminal A breast cancer." (PMID 32257110, 2020). "In fact, breast cancer cells with high HJURP levels are more sensitive to radiation and exhibit a higher rate of apoptosis than those with low levels." (PMID 30850008, 2019). "Several studies have reported that HJURP overexpression was observed in a majority of lung cancer and breast cancer tissue samples." (PMID 28410204, 2017). "Genes (G1) with high node centrality values in Basal II, such as HJURP and TPX2 have been linked to aberrant proliferation networks, cell invasion and metastasis in breast cancer, in line with the definition of BL1." (PMID 28351365, 2017). "Expression of HJURP was inconsistent, being overexpressed in 14 of 20 cancer types, especially colorectal cancer, breast cancer, sarcoma as well as lung cancer and underexpressed in 4 types." (PMID 28410204, 2017). "Expression level of HJURP was previously reported to correlate with glioblastoma cell survival, and was found to be a predictive biomarker for sensitivity to radiotherapy in breast cancer." (PMID 25484917, 2014). "HJURP mRNA level is a prognostic indicator of disease-free and overall survival in patients with infiltrating breast cancer and a predictive biomarker of radiosensitivity." (PMID 25243117, 2014). "HJURP mRNA levels were identified as a predictive marker of prognosis and of sensitivity to radiotherapy in breast cancer." (PMID 24039914, 2013).
breast carcinoma (continued). "In agreement, published data has previously shown that HJURP over expression is correlated with diminished survival of lung and breast cancer patients." (PMID 23638004, 2013). "Increased rates of chromosome loss with overexpression of both CENP-A and HJURP are consistent with observations in breast cancer where there is a correlation between increased levels of HJURP and CENP-A." (PMID 21980305, 2011). "Overexpression of HJURP has been observed in mammalian cancer cell lines, such as lung and breast cancers." (PMID 21980305, 2011). "To validate our findings, we used several independent breast cancer cohorts with previously reported microarray data deposited in the Gene Expression Omnibus (GEO) database, to compare mRNA level of HJURP in tumor tissue with patient survival." (PMID 20211017, 2010). "The current study is the first to report that HJURP is overexpressed in breast cancer cell lines and primary human breast cancer compared to non-malignant human mammary epithelial cells and normal breast tissues." (PMID 20211017, 2010). "In vitro studies in breast cancer cell lines showed that cells with high HJURP levels were more sensitive to radiation treatment and had a higher rate of apoptosis than those with low levels." (PMID 20211017, 2010). "The expression level of HJURP has an independent prognostic impact for both disease-free and overall survival in breast cancer, and is a predictive biomarker for radiotherapy." (PMID 20211017, 2010). "The goal of this study was to investigate the clinical significance of HJURP in breast cancer and its correlation with radiotherapeutic outcome." (PMID 20211017, 2010). "Poor clinical outcomes among patients with high HJURP expression were validated in five additional breast cancer cohorts." (PMID 20211017, 2010). "HJURP mRNA level is a prognostic factor for disease-free and overall survival in patients with breast cancer and is a predictive biomarker for sensitivity to radiotherapy." (PMID 20211017, 2010). "We measured HJURP expression level in human breast cancer cell lines and primary breast cancers by Western blot and/or by Affymetrix Microarray; and determined its associations with clinical variables using standard statistical methods." (PMID 20211017, 2010). "In this study we showed that HJURP mRNA levels are highly significantly correlated with CENPA mRNA levels in human breast cancer cell lines and primary breast tumors." (PMID 20211017, 2010). "Knock down of HJURP in human breast cancer cells using shRNA reduced the sensitivity to radiation treatment." (PMID 20211017, 2010). "In breast cancer, HJURP expression levels are higher than in normal breast tissue." (PMID 39649097, 2024). "Enrichment analysis of the differentially expressed genes suggested that HJURP might regulate breast cancer progression through the PI3K-AKT signaling pathway." (PMID 39139392, 2024). "Moreover, HJURP exhibits some oncogenic activities in various cancer types such as breast cancer and liver cancer." (PMID 35274047, 2022). "These suggested that HJURP might be a key regulator in breast cancer, but its roles in TNBC are not well understood." (PMID 35459269, 2022). "To determine whether HJURP involves in the progression of TNBC, we firstly examined the expression level of HJURP in breast cancer cells." (PMID 35459269, 2022). "Similarly, the upregulation and overexpression of HJURP has been observed in lung, ovarian and prostatic adenocarcinoma, and in breast carcinoma, as well as in gliomas." (PMID 35955489, 2022). "Aberrant HJURP expression has been observed in a cohort of 71 breast cancer patients." (PMID 32257110, 2020). "In human breast cancer, overexpression of HJURP may be similar to overexpression of mitotic kinases, such as Aurora kinases, which induce genomic instability, one of the hallmarks of tumor development." (PMID 33114545, 2020).
breast carcinoma (continued). "Furthermore, HJURP was reported to be overexpressed in lung cancer, and it has been proposed as an independent prognostic marker for luminal A breast carcinoma." (PMID 33114545, 2020). "HJURP proved to be an independent prognostic factor in Serous Ovarian Carcinoma and breast cancer." (PMID 31139013, 2019). "Furthermore, in breast cancer, elevated HJURP levels emerged as an independent prognostic marker of poor patient outcome, distinguishing aggressive tumors within the luminal A subtype." (PMID 28356341, 2017). "Additionally, it was observed that HJURP expression levels are increased in the majority of lung and breast cancers and correlate with poor survival prognosis." (PMID 23638004, 2013). "Notably, overexpression of HJURP has also been observed in breast cancer cells, where patients with elevated HJURP mRNA levels showed decreased survival rate and were more sensitive to radiotherapy." (PMID 21980305, 2011). "Furthermore, HJURP is a predictive marker for sensitivity of radiotherapy, indicating levels of HJURP mRNA and protein in breast cancer patients are clinically relevant." (PMID 20211017, 2010). "HJURP was expressed at higher level in breast cancer than in normal breast tissue." (PMID 20211017, 2010). "It has been reported that HJURP is involved in the DNA repair pathway, thus next we investigated whether the HJURP mRNA level is a predictive marker for radiotherapy in our cohort of breast cancer patients." (PMID 20211017, 2010). "Finally we designed small interfering RNA (shRNA) against HJURP and generated stable transfectants in a human breast cancer cell line (MDAMB231)." (PMID 20211017, 2010). "Thus overexpression of HJURP in human breast cancer may be similar to overexpression of mitotic kinases, such as Aurora kinases, which induce genomic instability that is one of the hallmarks for tumor development." (PMID 20211017, 2010). "The understanding of the roles that HJURP plays in DNA repair and cell death in response to DNA damage may provide new insights into the molecular mechanisms of breast tumor development and may help to improve breast cancer therapies." (PMID 20211017, 2010). "In a recent study, using RT-qPCR, two panels of transcripts related to the presence of CTCs (Panel 1: CK19, EpCAM, SCGB2A2 and Panel 2: EMP2, SLC6A8, HJURP, MAL2, PPIC and CCNE2), in two cohorts of breast cancer patients (metastatic and early), were evaluated." (PMID 37046848, 2023). "Because HJURP and YAP1 are both highly expressed in basal-like breast cancer, YAP1 as a transcriptional factor plays an important role in TNBC." (PMID 35459269, 2022). "Amongst the other highly significant upregulated CR genes by p-value and log2FC, SKA2, MKI67, HJURP, BIRC5, and CCNB1 are upregulated in breast cancer tissues and all five except for SKA2 have been identified as prognostic markers for breast cancer." (PMID 32457901, 2020). "Surprisingly, HJURP levels were significantly and positively correlated with CENPA levels in human breast cancer cell lines and primary breast tumors." (PMID 20211017, 2010). "Further investigation of the interaction between HJURP and CENPA for breast cancer development will be carried out in our future studies." (PMID 20211017, 2010). "In our present study, we evaluated two panels of transcripts related with the presence of circulating tumor cells (CTCs) (Panel 1: CK19, EpCAM, SCGB2A2 and Panel 2: EMP2, SLC6A8, HJURP, MAL2, PPIC and CCNE2) in two cohorts of breast cancer patients (metastatic and early)." (PMID 36831613, 2023). "Although we found few genetic alterations in the HJURP locus by inspection of these CGH microarray data, the protein levels of HJURP were elevated in about 50% of these breast cancer cell lines when compared to immortalized but non-malignant mammary epithelial cells 184A1N4, 184B5, and S1." (PMID 20211017, 2010).